APOE (apolipoprotein E)
Diseases named in the same sentence as APOE in open-access papers (continued):
Sharing a sentence is not in itself a finding about the gene and the disease.
atherosclerosis (continued). "During progression of atherosclerosis, apoE-deficient mice shows obviously decreased number in Treg cells as compared with wild type littermates." (PMID 29584779, 2018). "Concerning metabolic syndrome, atherosclerosis-prone apolipoprotein E (ApoE)(−/−) ataxia telangiectasia mutated (ATM)(+/−) mice were used to investigate the effects of a high-calorie diet on DNA damage and metabolic syndrome in the liver." (PMID 30513990, 2018). "In the present study, we assessed the effects of lentiviral-mediated Lp-PLA2 and/or YKL-40 RNAi on the progression of atherosclerosis and the associated inflammatory process following collar-induced atherosclerosis in apoE-/- mice." (PMID 30138439, 2018). "To test the effect of CYP27A1 deficiency on the development of atherosclerosis, we previously crossed Cyp27a1 knockout (KO) mice with Apolipoprotein E (ApoE) KO mice, and fed the offspring with a Western diet (WD) for 3 and 6 months." (PMID 29191818, 2018). "Transferring choline diet-induced TMAO production via fecal transplantation in apoE-deficient (−/−) mice resulted in an increased atherosclerosis risk." (PMID 30347638, 2018). "Some reports have shown that periodontitis increases the risk of atherosclerosis in vivo and in vitro, and that periodontitis worsens in the apolipoprotein E (ApoE)−/− hyperlipidemia model." (PMID 29859535, 2018). "The objective of this study is to explore the role of the MR specifically in SMCs in the progression of atherosclerosis and the associated vascular inflammation in vivo in the apolipoprotein E knockout (ApoE−/−) mouse model." (PMID 30038907, 2018). "Other chemokine receptors such as CCR5 and CX3CR1 are also important to the recruitment of monocytes to atherosclerotic plaques as ablation of these receptors and CCL2 prevents monocytosis and dramatically reduces atherosclerosis in apoE‐deficient mice." (PMID 29364567, 2018). "In a previous study, loss of functional FXR in apolipoprotein E-deficient (ApoE-/-) mice, a mouse model of atherosclerosis, resulted in more severe lipid metabolism defects and enhanced aortic plaque formation." (PMID 30319417, 2018). "Another supporting evidence for the protective role of GDF15 on atherosclerosis came from a study using ApoE deficient mouse model of atherosclerosis." (PMID 30542297, 2018). "Involvement of ICAM-1 in the progression of atherosclerosis in the ApoE-deficient mice model has been previously reported." (PMID 30524759, 2018). "Our findings firstly demonstrated that LPSp can effectively ameliorate hyperlipidemia and inflammatory/oxidative responses to prevent atherosclerosis progression when administered orally to HFD-fed apoE-deficient mice." (PMID 29584779, 2018). "In atherosclerosis-prone apolipoprotein E-deficient mice, recombinant adeno-associated virus-mediated CYP2J2 gene overexpression, which is associated with increased EET levels, prevented the development of high-fat diet induced atherosclerosis." (PMID 29966295, 2018). "In order to study the role and activity of nNOS in spontaneous atherosclerosis, nNOS deficient mice model (nNOS-KO) was combined with the atherogenic ApoE-KO mice model." (PMID 30140678, 2018). "Apolipoprotein E-deficient (ApoE−/−) mice have been widely used as models of atherosclerosis because they can develop hyperlipidemia and atherosclerotic lesions similar to those found in humans." (PMID 30526612, 2018). "In recent animal experiments of atherosclerosis, almost all the researches are carried out in ApoE deficient background." (PMID 29922166, 2018).
atherosclerosis (continued). "Consistently, both endogenous mouse ApoCI expression in an ApoE deficient background and overexpression of human APOCI in either a wild type or an ApoE deficient background can lead to hypertriglyceridemia and atherosclerosis in mice." (PMID 29346450, 2018). "Angptl3 deletion was also reported to reduce the development of atherosclerosis in apolipoprotein E (apoE)-deficient mice." (PMID 29440457, 2018). "The control of miR146a expression by apoE provides new insight to explain the susceptibility of Apoe−/− mice to atherosclerosis and sepsis." (PMID 29789495, 2018). "Apolipoprotein E-deficient (ApoE−/−) mice develop atherosclerosis with severe PAH when fed a high-fat diet (HFD) and have increased levels of endothelin (ET)-1." (PMID 29261014, 2018). "Genetic deletion of p66SHC encoding gene significantly reduced oxidant levels and atherosclerosis in apolipoproteinE-knock out (ApoE-KO) mice, suggesting an important role for the oxLDL-mediated oxidative stress in the development of atherosclerosis." (PMID 29337890, 2018). "Our data show that inactivating the NE gene causes a substantial reduction in the extent of atherosclerosis in ApoE‐deficient mice fed an HFD." (PMID 29437605, 2018). "The authors reported reduced atherosclerosis, in spite of increased serum cholesterol, in IL-18 deficient apoE(−/−) mice." (PMID 30524759, 2018). "Apolipoprotein-E gene-deficient mice (ApoE −/− mice) have been shown to develop hyperlipidemia and atherosclerosis as well as hypertension and endothelial dysfunctions." (PMID 30200674, 2018). "Macrophage-specific NF-κB knockout in apolipoprotein E-deficient mice reduced the high-fat-diet-induced acceleration of atherosclerosis." (PMID 29543732, 2018). "AC were shown to inhibit atherosclerosis in apolipoprotein E (ApoE)-deficient mice, and AC reduced the risk of myocardial infarction in another study." (PMID 30106986, 2018). "For example, a heat shock protein, which acts as TLR4 agonist, was found to show preventive effects against hyperlipidemia and atherosclerosis when administered orally to apoE-deficient mice." (PMID 29584779, 2018). "In an ApoE-deficient mouse model of atherosclerosis, these two drugs counteracted ER stress-induced inflammation in macrophages." (PMID 29921793, 2018). "In the current study, by generating NE and Apolipoprotein E (ApoE) double knockout mice, and utilizing a highly potent and selective NE inhibitor, we provide direct evidence to support a causal role for NE in atherosclerosis." (PMID 29437605, 2018). "The differential effect of inulin on atherosclerosis development in APOE-deficient mice versus E3L mice is therefore likely mouse model-specific." (PMID 29401645, 2018). "In contrast CD39 is down-regulated in atherosusceptible regions of the murine aorta and CD39 deficient mice on an Apolipoprotein E (ApoE)−/− background exhibited increased atherosclerosis." (PMID 29126223, 2018). "For the evaluation of lipid metabolism or atherosclerosis, male ApoE-deficient mice was usually used, because estogens strongly influence lipid and cholesterol metabolism in female mice." (PMID 29438441, 2018). "ApoE deficient (ApoE−/−) mice can spontaneously develop atherosclerosis which covers the whole spectrum of human lesions." (PMID 29922166, 2018). "IL-1Ra has been documented to have anti-atherosclerotic roles, as IL-1Ra knockout mice on an ApoE-deficient background develop more severe atherosclerosis." (PMID 30305306, 2018).
atherosclerosis (continued). "Elevated 27-OHC via deletion of CYP7B1 that metabolizes 27-OHC promotes atherosclerosis via a proinflammatory process involving estrogen receptor alpha in apoE-deficient mice." (PMID 30283400, 2018). "In this study, we aimed to study an atherosclerosis rabbit model; to this end, we used induction of atherosclerosis by consumption of a high-fat diet in ApoE-deficient mice." (PMID 30105261, 2018). "Systemic treatment with cortistatin reduced the number and size of atherosclerotic plaques in carotid artery, heart, aortic arch and aorta in acute and chronic atherosclerosis induced in apolipoprotein E-deficient mice fed a high-lipid diet." (PMID 28406244, 2017). "In mice, deletion of the insulin receptor (IR) from vascular endothelial cells in the apolipoprotein-E-deficient mice (ApoE−/−) leads to an increased rate of atherosclerosis development." (PMID 28752048, 2017). "Comparative assessment of global and local PWV in ApoE-/- and WT mice revealed that vascular stiffening caused by early atherosclerosis is inhomogeneously distributed over the length of a large vessel." (PMID 28207773, 2017). "We investigated the potential therapeutic effect of cortistatin in two models of atherosclerosis in genetically susceptible apoE−/− mice fed a high-lipid diet." (PMID 28406244, 2017). "The role of ApoE has been well established in atherosclerosis as ApoE-deficiency results in the development of atherosclerosis in mice." (PMID 28344760, 2017). "To directly examine the role of PAR-2 in atherosclerosis, we generated apolipoprotein E/PAR-2 double-deficient mice." (PMID 28959204, 2017). "We first addressed the frequency of ILC2 in atherosclerosis-susceptible apolipoprotein e-deficient (Apoe−/−) mice fed normal chow diet." (PMID 28589929, 2017). "Surprisingly, some studies reported that Nrf2-deficient mice when crossed with ApoE-null hypercholesterolemic mice were protected against atherosclerosis." (PMID 29113088, 2017). "In conclusion, treatment with rTM suppressed stress-induced autophagy overactivation in ECs, provided ECs protective effects, and decreased atherosclerosis in apolipoprotein E deficient mice." (PMID 28607460, 2017). "Specifically, it has been shown that deficiency in TLR2 or TLR4 results in diminishing inflammation in the prominent mouse models of atherosclerosis [apolipoprotein E (ApoE)- and LDL receptor-deficient mice;]." (PMID 28769820, 2017). "The pharmacological inhibition of Fabp4 significantly protected against atherosclerotic plaque formation in the ApoE-deficient animal model of atherosclerosis." (PMID 29064389, 2017). "Previous studies using ApoE−/− mice heterozygous for both IR and the insulin receptor substrate-1 (IRS1) protein found that the apolipoprotein-E deficiency resulted in increased atherosclerosis development." (PMID 28752048, 2017). "We have previously characterized MGL deficiency and the endocannabinoid system in the context of atherosclerosis development by generating apolipoprotein E/MGL double knockout (DKO) mice." (PMID 28380440, 2017). "Mice deficient for the apolipoprotein E (ApoE-/-mice) with high-cholesterol diet were studied as an age-dependent model of atherosclerosis." (PMID 28982198, 2017). "Clearly APOE polymorphisms represent just a brick in the Great Wall of atherosclerosis building, yet still having a definite weight in the physiopathology of this complex disease." (PMID 28249002, 2017).
atherosclerosis (continued). "Hyperglycemia, for example, can increase the expression of NOX1 in human aortic ECs, while inhibition of NOX1 in diabetic apolipoprotein-E (ApoE) deficient mice reduces atherosclerosis development." (PMID 28612009, 2017). "Genetic inactivation of Tnfsf12 reduced atherosclerosis extension and severity in diabetic ApoE deficient mice." (PMID 28447667, 2017). "ApoE polymorphisms modulate susceptibility to many diseases, namely neurodegenerative disorders and atherosclerosis, as well as psoriasis." (PMID 28911329, 2017). "Loss of IRF5 expression reduced aortic lesion and necrotic core size in atherosclerosis-prone apolipoprotein E-deficient (ApoE-/-) mice." (PMID 28698173, 2017). "Taken together, these data show that the global deletion of Cd39 is protective against development of atherosclerosis in ApoE-deficient mice." (PMID 28487312, 2017). "Atherosclerosis is a complex multifactorial disease and the apolipoprotein E (APOE) polymorphism has been associated to vascular complications of atherosclerosis." (PMID 28249002, 2017). "C57BL/6J mice transplanted with bone marrow from apoE-deficient mice displayed increased atherosclerosis, while apoE-deficient mice receiving wild-type murine bone marrow cells displayed reduced atherosclerosis and lower hypercholesterolemia." (PMID 28355284, 2017). "DKK3-deficient mice were crossed with apolipoprotein E-/- mice to evaluate atherosclerosis development and vessel injury-induced neointimal formation." (PMID 28674110, 2017). "Genetic depletion of miRNA-126-5p promotes EC proliferation and limits atherosclerosis in apolipoprotein E–deficient mice." (PMID 28878126, 2017). "PTX3 deficiency in model mice (ApoE mice) was associated with atherosclerosis development and increased macrophage accumulation within atherosclerotic plaques as well as with more pronounced inflammatory profiles in vascular walls." (PMID 28536575, 2017). "We have found that prolonged administration of agmatine significantly inhibited atherosclerosis in apoE-/- mice; such an action was associated with the elevation of HDL in plasma." (PMID 28777310, 2017). "Recently, a study using a conditional knockout mouse model showed that HIG2 mediates neutral lipid accumulation in macrophages and contributes to atherosclerosis in apolipoprotein E-deficient background." (PMID 29256392, 2017). "This is important, as endothelial dysfunction is considered to underlie atherosclerosis development in ApoE‐/‐ mice." (PMID 27935022, 2017). "Here, we report a reduction in atherosclerosis in response to pharmacological stimulation of thermogenesis linked to increased HDL levels in APOE*3-Leiden.CETP mice." (PMID 28422089, 2017). "Recombinant IL‐12 accelerates the formation of atherosclerotic lesions in apoE−/− mice, while IL‐12 deficiency (IL‐12−/−/apoE−/−) resulted in reduced atherosclerosis." (PMID 28409825, 2017). "In two different models of atherosclerosis development in which the rate of lesion progression was varied by diet (high-fat or chow), overexpression of M3 in apoE-/- mice caused reductions in plaque size and macrophage content." (PMID 28282403, 2017). "Apolipoprotein E (ApoE) is a multifunctional protein, and its deficiency leads to the development of atherosclerosis in mice." (PMID 28344760, 2017). "Diabetic apolipoprotein E (ApoE) deficient mice that are also devoid of Ager (gene encoding RAGE) display reduced atherosclerosis and lower expression of vascular cell adhesion molecule (VCAM)-1 and tissue factor." (PMID 29259621, 2017). "More recently, a study using Apolipoprotein E-deficient (ApoE-/-) Batf3-/- mice has proposed that Batf3-dependent DCs promote atherosclerosis through induction of Th1 responses in the aorta." (PMID 28771609, 2017). "The oral administration of rebamipide decreased plaque formation in atherosclerotic lesions as well as the markers of metabolic disorder in ApoE-deficient mice with atherosclerosis." (PMID 28241014, 2017).
atherosclerosis (continued). "Mice deficient in both SR-B1 and apolipoprotein E (apoE) rapidly develop dyslipidemia, atherosclerosis and spontaneous myocardial infarction on a normal chow diet, resulting in premature death by 6–8 weeks of age5,6." (PMID 29273789, 2017). "In a recent study, polyethylene glycol-polyethyleneimine nanoparticles were used as vectors for microRNA delivery targeting E-selectin of inflamed endothelium of ApoE-deficient mice, which ameliorated endothelial inflammation and atherosclerosis." (PMID 28095860, 2017). "A chronological analysis of atherosclerosis in the apoE deficient mouse has shown that the sequential events involved in lesion formation are strikingly similar to those in well-established larger animal models of atherosclerosis and in humans." (PMID 28178661, 2017). "Oil Red O staining and ELISA assay showed that Tan IIA suppressed the progress of atherosclerosis and reduced the levels of inflammatory cytokines in serum of apolipoprotein E deficient (ApoE–/–) mice." (PMID 28412716, 2017). "A recent study reported that RDN inhibited atherosclerosis formation in normotensive apolipoprotein E-deficient (ApoE−/−) mice fed a high-fat diet." (PMID 28450836, 2017). "Apolipoprotein E-deficient (ApoE-/-) mice are considered to be an important model of atherosclerosis, since they develop atherosclerotic lesions of morphology similar to those observed in humans." (PMID 28207773, 2017). "Animal studies have indicated that IL-33 reduces macrophage foam cell formation and inhibits the development of atherosclerosis in apolipoprotein E-deficient mice." (PMID 28045954, 2017). "Paralleling, what happens in humans, apoE-deficient (apoE−/−) mice, one of the most widely used murine model of atherosclerosis, exhibit accelerated atherosclerosis progression when fed a high-fat high-cholesterol (HFHC) diet." (PMID 28316603, 2017). "To investigate the effects of rebamipide on atherosclerosis, we fed a western diet to ApoE–deficient (ApoE-KO) mice to induce atherosclerosis and administered rebamipide or statin, used as the positive control." (PMID 28241014, 2017). "In our in vivo study, EZH2 promoted the development of atherosclerosis in aortas of apoE−/− mice, which was associated with the higher DNA methylation level on ABCA1 promoter." (PMID 27295295, 2016). "The hypercholesterolaemic apolipoprotein E deficient (ApoE−/−) mouse is a well-established model for atherosclerosis." (PMID 27401543, 2016). "A previous study has demonstrated that experimental periodontitis induces serum amyloid A (SAA) in the liver and peripheral blood of ApoE-deficient mice as an atherosclerosis model." (PMID 27799725, 2016). "Very low circulating concentration of ApoE in humans is associated with early onset atherosclerosis." (PMID 27755538, 2016). "A transgenic mouse that overexpresses PP5 in T cells in a doxycycline-inducible manner is currently being developed to test if PP5 causes a lupus-like phenotype and accelerated atherosclerosis in the apoE−/− model." (PMID 28239687, 2016). "The present study characterized heterozygous glucokinase knockout apolipoprotein E deficient mice (GK+/−ApoE−/−), a novel mouse model of diabetes and atherosclerosis." (PMID 27774459, 2016). "Topical 12-O-tetradecanoylphorbol-13-acetate (TPA) was applied to the ears twice per week for 8 weeks in atherosclerosis-prone apolipoprotein E deficient (ApoE−/−) mice." (PMID 27401543, 2016). "These pro-atherogenic effects are mediated by the cellular receptor for LPS, TLR4 and loss of this receptor in TLR4, ApoE double knockout mice results in reduced atherosclerosis." (PMID 27168152, 2016). "In aged apolipoprotein E (ApoE)-deficient mice with atherosclerosis, smooth muscle cells beneath intimal plaques take on LTo-like properties and secrete CXCL13 and CCL21 to drive tertiary lymphoneogenesis." (PMID 27752256, 2016).